RN7SL692P (RNA, 7SL, cytoplasmic 692, pseudogene)
Gene: Miscellaneous RNA gene on chromosome 1 (92,974,827 to 92,975,114, reverse strand). Ensembl gene ENSG00000239710.
Homologues: Orthologues: chimpanzee Metazoa_SRP (96% identical), macaque Metazoa_SRP (93% identical). Paralogues in human: RN7SL3 (81% identical), RN7SL1 (81% identical), RN7SL2 (80% identical), RN7SL566P (80% identical), RN7SL597P (79% identical), RN7SL448P (78% identical), RN7SL664P (78% identical), RN7SL799P (78% identical), RN7SL126P (78% identical), RN7SL296P (77% identical), RN7SL559P (77% identical), RN7SL630P (77% identical), and 702 more.